CCNA2 (cyclin A2)
Diseases named in the same sentence as CCNA2 in open-access papers (continued):
Sharing a sentence is not in itself a finding about the gene and the disease.
breast cancer (continued). "Tamoxifen could induce CCNA2 upregulation in breast cancer cells, and genistein could induce G2 M phase arrest in breast cancer cell lines." (PMID 40345591, 2025). "Our results indicate that SCFAs could inhibit the progression of different breast cancer cells through the modulation of proliferative and cell cycle pathways, leading to cyclin A2- and B1-dependent cell arrest and apoptosis." (PMID 39200243, 2024). "In ER− parental and palbociclib-resistant MDA-MB-468 (Rb-deficient) breast cancer cells, DDX also downregulated cyclin E2 and cyclin A2 and unexpectedly restored the presence of the cell cycle repressor Rb, which is an integral part of the cell cycle checkpoint inhibiting the progression past G1." (PMID 38473336, 2024). "The inclusion of three additional targets (CCNA2, PCNA, and KIF23) within the APIS BC Subtyping Kit, known to be associated with breast cancer proliferation and expressed across all cell cycle stages, allows for the generation of a more complete proliferation measure." (PMID 38337757, 2024). "In addition to having tamoxifen resistance, CCNA2 has a significant predictive value for the prognosis of estrogen receptor (ER)+ breast cancer patients." (PMID 36880057, 2023). "Moreover, CCNA2 had significant predictive value for the prognosis of ER+ breast cancer patients as well as tamoxifen resistance." (PMID 31285741, 2019). "Taken together, these data suggest that CCNA2 may be a prognostic biomarker for ER+ breast cancer and tamoxifen resistance." (PMID 31428132, 2019). "It has been reported that a high CCNA2 expression promotes cell proliferation in hepatoma and might help monitor chemotherapy efficacy in breast cancer." (PMID 30765611, 2019). "Interestingly, the GATA3 down-regulation is required for the progestin-induced upregulation of cyclin A2(CCNA2) and for progestin-induced in vivo and in vitro breast cancer cell growth." (PMID 27454576, 2016). "Here, our results demonstrate that SL4 was able to induce cell cycle arrest at the G2/M phase in breast cancer cells by activating the MAPK pathway and subsequently regulating cell cycle-associated proteins, including p21, cdc25C, cdc2, cyclin B1 and cyclin A2." (PMID 27819344, 2016). "All these data indicates that CCNA2 confers poor prognosis in ER+ breast cancer." (PMID 24622579, 2014). "Importantly, we demonstrate that GATA3 downregulation is required for progestin-induced upregulation of cyclin A2 and for progestin-induced in vitro and in vivo breast cancer cell growth." (PMID 25479686, 2014). "Since high expression of CCNA2 confers poor DMFS, DFS, RFS and OS in ER+ breast cancer patients and tamoxifen is one of the most widely used drugs for the management of those ER+ patients, CCNA2 may play a potential role in tamoxifen resistance." (PMID 24622579, 2014). "Finally, we demonstrated that GATA3 downregulation is essential for cyclin A2 upregulation and progestin-driven breast cancer growth." (PMID 25479686, 2014). "In addition, cyclin A2 expression levels have been shown to have independent prognostic value in breast cancer patients, with increased expression correlating with poor outcome." (PMID 25479686, 2014). "This suggests that cyclin A2, could play an important role in prostate aggressiveness as demonstrated for breast cancer cells." (PMID 22095224, 2012). "Higher cyclin A2 expression may lead to poor patient prognosis for several other tumors, among them breast cancer." (PMID 20029639, 2009). "Besides, Cyclin A2 also could be induced by c-Myc, thereby promoting cell cycle in mammary cancer cells." (PMID 31888761, 2019). "Finally, five hub genes (TPX2, KIF2C, CDCA8, BUB1B, and CCNA2) were identified for further research, which might be used as promising biomarkers to evaluate the distant metastasis of breast cancer." (PMID 31285741, 2019).
breast cancer (continued). "However, whether ER+ breast cancer patient with CCNA2 overexpression could benefit from the repression of CCNA2, or in other words, whether CCNA2 is a promising target for preventing or could reverse tamoxifen resistance still needs more experimental support." (PMID 24622579, 2014). "In breast cancer, the antiproliferative effects of NR1D1 were achieved by targeting cyclin A2 and interfering with the cancer cell cycle." (PMID 38480634, 2024). "The five potential prognostic biomarkers, i.e., Aurora Kinase A (AURKA), BUB1 Mitotic checkpoint serine/threonine kinase B (BUB1B), Cyclin A2 (CCNA2), Cyclin B2 (CCNB2), and PDZ binding kinase (PBK) were upregulated in breast cancer." (PMID 36980449, 2023). "Elevated expression of the five hub genes AURKA, BUB1B, CCNA2, CCNB2, and PBK are related to poor OS in breast cancer patients." (PMID 36980449, 2023). "AURKA, BUB1B, CCNA2, CCNB2, and PBK, and these hub genes obtained were found to be upregulated (based on log2fold change value) in breast cancer." (PMID 36980449, 2023). "The aberrant expression of CCNA2 is related to reduce survival in patients with HCC and breast cancer." (PMID 36317111, 2022). "We found that eight cyclins (CCNA2, CCNB1, CCNB2, CCND2, CCNE1, CCNE2, CCNF, CCNO) were differentially expressed between breast cancer and normal tissue samples, with the cut-off criterion of log2(fold change) >1, p < 0.05." (PMID 33791304, 2021). "Genes related to proliferation (MKI67, CCNA2), differentiation (EPCAM, CDH1), epithelial to mesenchymal transition (VIM, SNAI2), pluripotency and breast cancer stem cells (SOX2, NANOG, CD44) were included." (PMID 34090457, 2021). "We previously demonstrated that forced downregulation of miR-10b-3p in breast cancer perturbed BUB1, PLK1, and CCNA2 expression, hence accelerated tumor progression." (PMID 33230261, 2021). "The expression levels of CCNA2, DEPDC1, and TTK (DOE-A) were significantly higher in BL/TNBCs than in luminal breast cancer cell lines." (PMID 34172056, 2021). "Noticeably, PTTG1 gene, the transcriptional promoter of CDK1, was up-regulated in breast cancer; ZBTB16 gene was the transcriptional suppressor of CCNA2, and its expression was down-regulated in overlapping DEGs." (PMID 33083112, 2020). "High expression of MAD2L1, CCNA2 and FUT8-AS1 and low expressions of LINC01279, RAD51-AS1 and CARMN were correlated with significantly worse OS in breast cancer patients, while Other candidate hub genes expression were not significantly relevant to OS." (PMID 33128008, 2020). "As a result, there were nearly 2.1% (CDC20, CDK1), 1.2% (RRM2), 0.9% (BUB1B), 0.8% (CCNA2), 0.7% (CCNB2) of breast cancer samples included in cBioPortal had genetic changes." (PMID 33083112, 2020). "We tested two predicted OCN pairs in each cancer type, including NCSTN and DNM1, and NCSTN and OGT in liver cancer; CCNA2 and PTP4A1, and HIF1A and PARP1 in lung cancer; and CCNA2 and PTP4A1, and PLK1 and PTP4A1 in breast cancer." (PMID 31097707, 2019). "We observed that transfection with SALL1 significantly increased the gene expressions of Cyclin A2, Cyclin B1, Cyclin E1, CDK2 and CDK4 in breast cancer MDA cells, which are important for checkpoint regulation in G1-S transition and S phases." (PMID 29625565, 2018). "In this study we evaluate the potential MGMT’s role in control of therapeutic, clinically relevant, cell cycle regulators involved in breast cancer oncogenesis (CDC2, TOP2A, AURKB, CDC20, KIF20A, Cyclin A2, Cyclin B2, Cyclin D1)." (PMID 30038716, 2018). "Our results demonstrate novel roles for cyclin A2 in regulating HR repair and determining sensitivity to DNA cross linkers and PARP inhibitors in breast cancer cells." (PMID 29207607, 2017).
breast cancer (continued). "Mechanistically, SL4 induced G2/M arrest in breast cancer cells by activating the MAPK/p21 signaling axis, which subsequently regulated the activity of the CDK1/cyclin A2 and CDK1/cyclin B1 complexes." (PMID 27819344, 2016). "Taken together, these results account for a role of GATA3 as a negative regulator of MPA-induced cell proliferation through prevention of cyclin A2 upregulation, and demonstrate the requirement of GATA3 downregulation for progestin-driven breast cancer growth." (PMID 25479686, 2014). "Indeed, the knockdown of FBXW9 increased p21 mRNA expression while mRNA levels of CCNA2 and CCNB1 were decreased in breast cancer cells." (PMID 36982338, 2023). "Meanwhile, inhibiting miR-125b using LNA inhibitor in the miR-125b-high MDA-MB-231 and MDA-MB-415 breast cancer cells resulted in increased E2F3, CDK2, CCNA2 and Bak1 protein expression and increased phosphorylation of Rb, which is indicative of increased G1-S progression with miR-125b inhibition." (PMID 38093346, 2023). "Previous investigators have found that cyclin CDK1, CCNB1 and CCNA2 are commonly overexpressed in TNBC and correlated with worse OS in breast cancer, so they could act as novel biomarkers for TNBC treatment." (PMID 37667382, 2023). "Notch signalling regulates the expression levels of Cyclin A2 and B19, which are negative prognostic markers of breast cancer." (PMID 35318302, 2022). "Nevertheless, whether these drugs could exert therapeutic effects on breast cancer by inhibiting the over-expression of RRM2, CDK1 and CCNA2, or whether CCNB2, BUB1B and CDC20 are promising therapeutic targets still need to be supported by further research." (PMID 33083112, 2020). "In breast cancer, NEK5-dependent CCNA2 overexpression promotes the proliferation of tumour cells." (PMID 31285741, 2019). "The aberrant expression of CCNA2 could be detected and closely related to reduced survival in HCC and breast cancer." (PMID 31043166, 2019). "Interestingly, the analysis of gene expression databases of different cohorts of breast cancer patients reveals that those expressing high levels of PLK1, BUB1 or CCNA2 exhibit lower disease-free survival when compared to those expressing low levels." (PMID 23125021, 2012). "We further showed that the expression of E2F3, CDK2 and CCNA2 transcripts are negatively correlated with expression of miR-125b but not that of the homologous miR-125a in breast cancer patients, supporting an inhibitory relationship between miR-125b and these cell cycle regulators." (PMID 38093346, 2023). "Notably, we identified that CCNA2 and CCNB2 were target genes of PTTG1 in breast cancer." (PMID 32272902, 2020). "Moreover, six hub genes were selected and validated in clinical sample for further analysis owing to the high degree of connectivity, including CDK1, CCNA2, TOP2A, CCNB1, KIF11, and MELK, and they were all correlated to worse overall survival (OS) in breast cancer." (PMID 31428132, 2019). "In vivo data showed that CCNA2 expression was down-regulated in MCF-7 tumor xenografts treatment with tamoxifen compared with control (P = 0.01), which indicates that tamoxifen could decrease CCNA2 expression in ER+ breast cancer cells." (PMID 24622579, 2014). "However, the association between CCNA2 expression levels and DMFS in ER- breast cancer patients is not significant (P = 0.3)." (PMID 24622579, 2014). "Unlike CCNB1, CCNA2, and CDK1, currently, the remaining genes (TOP2A, KIF11, and MELK) are not found to be associated with cell cycle; their dysfunctions might still affect the progression and prognosis of breast cancer." (PMID 31428132, 2019). "It has been reported that in breast cancer, NIMA (never in mitosis gene a)-related kinase 5 (NEK5)-dependent CCNA2 overexpression encourages the proliferation of tumor cells." (PMID 36880057, 2023).
breast cancer (continued). "Notably, CDK1, CCNA2, P4HA1, PAICS, and RAD51 showed a CERES score higher than zero in most breast cancer cell lines, indicating that they might not be essential to breast cancer." (PMID 34745136, 2021).
lung carcinoma (61 papers, 2010 to 2024). "Increased CHK1/2 activity by Tax during S phase restricts the CDK-dependent phosphorylation of FOXM1, preventing the premature expression of G2/M genes, including those encoding cyclin-dependent kinase 4, cyclin B1, and cyclin A2, all common DEGs in lung cancer." (PMID 39228892, 2024). "The SNP (rs769236) on the CCNA2 promoter may be associated with an increased risk of colon, liver, and lung cancer." (PMID 33619234, 2021). "And some studies have shown that single-nucleotide polymorphism (SNP) on CCNA2 promoter (rs769236) may be correlated with occurrence of colon, liver, and lung cancer." (PMID 33195410, 2020). "The increased expression of Ccna2 has been documented in various tumor types including lung cancer, and it has been proposed to be a biomarker for cancer diagnosis." (PMID 39273313, 2024). "In consistence with previous report, TIM-4 overexpression promoted proliferating cell nuclear antigen (PCNA), Cyclin A2, Cyclin B1 expression in lung cancer cells." (PMID 36806050, 2023). "DNAH17‐AS1 has been shown to promote tumorigenesis and metastatic ability of non‐small cell lung cancer (NSCLC) cells through regulation of miR‐877‐5p/CCNA2 pathway." (PMID 37933082, 2023). "In this study, we found that the expression of BUB1, CCNA2, CDC20 and KIF11 increased after inhibitor resistance compared with inhibitor-sensitive lung cancer samples, and these targets were associate with cell cycle, cell proliferation, DNA damage and EMT." (PMID 36176446, 2022). "More importantly, LINC00665- miR-let-7b- CCNA2 was identified as a novel key ceRNA network for its possible oncogenic function in lung cancer." (PMID 33627711, 2021). "Published literature indicates that CCNA2 is overexpressed in multiple tumors, including breast, colorectal, gastric, pancreatic, and lung cancers." (PMID 33927744, 2021). "Studies have shown that CCNA2 is often overexpressed in lung cancer, colorectal cancer, and liver cancer." (PMID 34880385, 2021). "Next, we evaluated the diagnostic values of the CCNA2 and TGFB2 risk genes through ROC curve analysis of the lung cancer diagnoses." (PMID 33195410, 2020). "Several research teams have reported the prognostic significance of CCNA2 in lung cancer but the results are controversial." (PMID 30369945, 2018). "Results showed that the mRNA expression of BIRC5, SHCBP1, CCNA2, SKA3 and GINS1 in LUAD and LUSC tissues were all significantly higher than that in normal tissues, whereas only BIRC5 and CCNA2 protein expression in lung cancer tissues were much higher than those in the normal lung tissues." (PMID 34806315, 2022). "Furthermore, like LCAT3 knockdown, FUBP1 knockdown also suppressed the migration of A549 and Calu1 lung cancer cells, and triggered G1 arrest by significantly reducing the levels of cyclin A2 and cyclin D1." (PMID 34274028, 2021). "Studies have also shown that cyclin A2 and B1 expressions are prognostic biomarkers of lung cancer." (PMID 33195410, 2020). "Compared to primary lung cancer, all the expression of hub genes increased in lymph node metastasis samples, and the expression of BUB1, BUB1B, CDK1, CCNA2 and CDC20 were related to peritoneum metastasis." (PMID 36176446, 2022). "Real-time PCR and Western blot analysis revealed that silencing PLPP4 repressed the mRNA and protein expression levels of critical cell cycle regulators of the G1/S checkpoint CCND1, CCNA2 and CCNB1 in lung carcinoma cells." (PMID 28851360, 2017). "The protein expression of several cyclins including cyclin A2, cyclin B1, cyclin D1, and cyclin E2 was markedly suppressed by GSK-3α knockdown in lung cancer cell lines." (PMID 27049759, 2016). "In mice with lung cancer, both of BA and SYK023 obviously decreased the levels of cyclin A2 and cyclin E2, whereas those of p15INK4b and p21CIP1 increased." (PMID 25909174, 2015).
lung carcinoma (continued). "Furthermore, under hypoxia, a factor that induces glycolysis, CCNA2 expression was upregulated in acute myeloid leukemia, and a similar relationship between hypoxia and CDT1 was found in lung cancer as well." (PMID 38794139, 2024). "In addition, the expression level of main hub genes (BUB1, CCNA2, CDC20, KIF11) was significantly higher in patients with EGFR TKI-resistant lung cancer tissues (GSE161584) than EGFR TKI-sensitive lung cancer tissues." (PMID 36176446, 2022). "It was found that TOP2A, CCNB1, CCNA2, CDK1, and TTK might be the critical target genes of lung cancer." (PMID 34616430, 2021). "CCNA2 might have prognostic value for progression free survival(PFS) and OS in patients with lung cancer." (PMID 33186389, 2020). "In addition, a previous study reported that CCNA2, CDC20, PBK, and TOP2A that interacted with CDK1 play vital roles in survival outcomes in human lung cancer." (PMID 32426332, 2020). "TOP2A, CCNB1, CCNA2, CDK1, and TTK may be the key target genes of lung cancer." (PMID 34616430, 2021). "Furthermore, CCNB1 and CCNA2 were vital in regulating cell cycle progression, while BRCA1 was involved in DNA repair, damage, and chromatin remodeling and DHX15 overexpression has been shown to promote proliferation and tumor metastasis, particularly in lung cancers." (PMID 38233752, 2024).